IL1B (interleukin 1 beta)
Diseases named in the same sentence as IL1B in open-access papers (continued):
Sharing a sentence is not in itself a finding about the gene and the disease.
gastric cancer (continued). "Two meta‐analyses were performed for the association of IL‐1B 31 polymorphism and gastric cancer risk." (PMID 26805397, 2016). "They found that the risk effects of variant allele of IL‐1B 31T on gastric cancer were more pronounced in H. pylori infection‐positive subgroup than in negative group 12." (PMID 26805397, 2016). "Stratified analysis observed that significantly increased gastric cancer risk was associated with IL‐1B 31 polymorphism in H. pylori‐positive subgroup, while null association was observed in H. pylori‐positive subgroup." (PMID 26805397, 2016). "Expression of transcripts encoding multiple pro-inflammatory cytokines previously implicated in gastric cancer was also elevated, including IL-6, IL-11, IL-1β, and TNFα." (PMID 26859571, 2016). "IL-1β has been associated with tumor development and invasiveness in different types of cancer, including gastric cancer." (PMID 27525003, 2016). "IL-1β, a ligand of IL-1R1, is well known as a pro-inflammatory cytokine and its over-expression is an essential risk factor in gastric cancer." (PMID 26870992, 2016). "Given the biological importance of IL‐1B 31 polymorphism, numerous studies have been carried out to explore its association with gastric cancer susceptibility." (PMID 26805397, 2016). "The correlated association between IL-1B and IL-1RN proinflammatory genotypes (IL-1B-511*T carriers and IL-1RN*2 homozygotes) and risk for gastric cancer was also determined (p < 0.001 and Pearson’s R = 0.300)." (PMID 26401131, 2015). "Individual genetic effects of 13 single nucleotide polymorphisms (SNPs) in PGC, PTPN11, TLR4, and IL1B on the susceptibility to gastric cancer and atrophic gastritis have been reported in our previous studies." (PMID 26158864, 2015). "Clinical studies have demonstrated a strong correlation between IL-1β polymorphisms and predisposition to gastric cancer development." (PMID 25528766, 2015). "In another epistatic interaction, the IL1B rs1143623 GC/CC genotypes showed an association with a reduced gastric cancer risk only if the PTPN11 rs12229892 GA/AA genotypes were absent." (PMID 26158864, 2015). "For PGC rs4711690 and IL1B rs1143623, rs4711690 GG/GC genotypes were associated with a reduced risk of gastric cancer and atrophic gastritis, but only in the presence of GC/CC genotypes at rs1143623." (PMID 26158864, 2015). "In the two-way analyses involving PTPN11, PTPN11 rs12229892 showed a significant interaction with IL1B rs1143623, influencing gastric cancer risk (P value for interaction = 0.034, interaction index = 1.64)." (PMID 26158864, 2015). "In this study, we found new SNP interactions among H. pylori-related host genes PGC, PTPN11, and IL1B modifying the susceptibility to atrophic gastritis and gastric cancer." (PMID 26158864, 2015). "Heterozygotes for IL-1B gene (IL-1B-511*T carriers) and both homozygotes and heterozygotes for T allele, also showed increased OR for developing gastric cancer." (PMID 26401131, 2015). "Polymorphisms in genes encoding pro-inflammatory cytokines have shown to increase the risk of gastric cancer, specifically interleukin-1β (IL1B-511/31, interleukin-1 receptor antagonist (IL1RN*2), and tumour necrosis factor A (TNFA-308)." (PMID 26186918, 2015). "Cytokine IL1B-31CC/-511TT gene polymorphisms have been shown to be related to gastric cancer and chronic gastritis development in patients infected by H. pylori." (PMID 24803922, 2014). "In a Korean population, the combination of increased mucosal IL-1β level and homozygosity for IL-1β -31T single nucleotide polymorphism (SNP) are both associated with increased risk for gastric cancer." (PMID 24223129, 2013). "IL1B–511T was associated with an increased risk of gastric cancer (intestinal type) (OR: 1.76, 95 % CI: 1.12–2.57)." (PMID 23995914, 2013). "Polymorphisms of the IL-1β that are predicted to increase IL-1β signaling have been shown to increase the risk of a number of human tumors, particularly gastric cancer." (PMID 24216700, 2013).
gastric cancer (continued). "This initial mouse model was followed by the H/K-ATPase-IL-1β transgenic mice, which progressed through the atrophy-metaplasia-dysplasia sequence and validated human genetic data that implicated the IL-1β gene locus as a major risk factor for gastric cancer." (PMID 24216700, 2013). "Conditional logistic regression analysis revealed that an increased risk of atrophic gastritis (odds ratio [OR]: 5.60) and gastric cancer (OR: 2.36) was associated with the IL1B–511C allele." (PMID 23995914, 2013). "The summary OR of gastric cancer risk associated with IL1B–511T, 231C, 13954T and IL1RN*2 was 1.26 (95 % CI: 1.03–1.55), 1.00 (95 % CI: 0.82–1.22), 1.37 (95 % CI: 0.94–2.00) and 1.20 (95 % CI: 1.01–1.41), respectively." (PMID 23995914, 2013). "A reduced risk of gastric cancer has been found in carriers of IL1B-31C of Asian origin and in carriers of IL10-592A (including all ethnic groups)." (PMID 24892619, 2013). "Using MNNG-induced gastric cancer model, it has been reported that administration of high-salt diet, calcium-deficient diet, catechol, or IL-1β promotes gastric cancer development." (PMID 24216700, 2013). "They found IL-1B −511T carriers were associated with a significantly increased risk of gastric cancer." (PMID 23704929, 2013). "They demonstrated that in IL1B–1473G carriers, the risk of the intestinal type gastric carcinoma increases." (PMID 23995914, 2013). "This indicates that the T allele can act as a proinflammatory allele in genotype IL1B–31T and both genotypes can constitute independent gastric carcinoma risk factors." (PMID 23995914, 2013). "The presence of various proinflammatory IL-10 genotypes, TNF-α, IL1B and the IL-1 receptor antagonist increases the risk of development of gastric carcinoma." (PMID 23995914, 2013). "IL-1β polymorphisms are associated with enhanced IL-1β production and increased risk of gastric cancer, IL-1β also inhibits gastric acid secretion." (PMID 23217022, 2012). "Of interest, Kong and co-workers suggest that the decreased expression of miR-7 in gastric cancer is associated with elevated expression of IL1B and an inflammatory response." (PMID 23115635, 2012). "This is illustrated by the association of specific IL-1β gene cluster polymorphisms that are linked not only to gastric cancer, but to H. pylori-associated hypochlorhydria." (PMID 22783255, 2012). "Additional studies have described a high risk for developing gastric cancer in patients infected with cagA-positive H. pylori that also expressed certain vacA alleles and who also possessed specific IL-1β and IL-1R polymorphisms." (PMID 22783255, 2012). "The IL-1B-511T polymorphism was associated with an increased risk of gastric cancer of the intestinal type (OR=1.76, 95% CI 1.12–2.57)." (PMID 19888225, 2010). "The IL-1B -511T and -31C alleles are associated with high levels of the cytokine and with severe inflammation or stomach cancer, in comparison to -511C and -31T, which are associated with low levels of IL-1β." (PMID 20979650, 2010). "The summary OR of gastric cancer risk associated with the IL-1B-511T polymorphism was 1.26 (95% CI 1.03–1.55) and the summary OR associated with the IL-1RN*2 allele was 1.20 (95% CI 1.01–1.41)." (PMID 19888225, 2010). "In Colombia, it has been observed that the presence of the 1082 (A/G) point mutation in the IL-10 gene (79%), together with another mutation in position 511 of the IL-1β gene (72%) and the Th1 immune response, increase the risk for gastric cancer in human populations." (PMID 39061325, 2024). "Although IL-1β increases IL-8 expression in various cells, including endothelial, epithelial, and smooth muscle cells, the molecular mechanism underlying IL-1β-induced IL-8 expression in gastric cancer is unknown." (PMID 39950099, 2024). "IL-1β is a pro-inflammatory cytokine released by immune cells, and its expression level is strongly associated with intense gastric inflammation, the progression of gastric cancer, and an unfavorable prognosis." (PMID 38068724, 2023).
gastric cancer (continued). "As for IL-1B-31 SNP, studies on the Brazilian population suggest that IL1B-31 C allele carriers may have enhanced IL-1β production at the gastric level, heightening the risk of developing severe chronic gastritis and gastric carcinoma." (PMID 36838318, 2023). "Furthermore, IL-1β gene polymorphisms were associated with an increased risk of gastric cancer, while the overexpression of this interleukin resulted in both gastric inflammation and cancer in mice." (PMID 35204842, 2022). "IL-1β was reported to be associated with gastric cancer, and TNF-α could function as a tumor promoter in the development of cancer." (PMID 36249016, 2022). "Similarly, in a mouse model of gastric cancer, IL1β signaling was linked to promoter methylation and transcriptional repression of E-cadherin, a gene that is critical in preventing cell migration and metastasis." (PMID 34901003, 2021). "In addition, infiltration of innate immune cells, such as neutrophils and macrophages, and a multiplicity of gastric cancer induced by H. pylori infection were significantly reduced in IL-1β-deficient mice." (PMID 32582201, 2020). "Two other independent studies have revealed that the “A” allele of IL-1B rs2853550 might reduce the risk of bowel disease and gastric cancer when was compared with the “G” allele." (PMID 32527212, 2020). "Additionally, IL-1B variants have been proved to be associated with gastric cancer susceptibility and inflammatory bowel disease." (PMID 32527212, 2020). "In gastric cancer, overexpression and the polymorphism of interleukin (IL)-1β are well known." (PMID 31040910, 2019). "In addition, we previously reported genetic polymorphisms in the promoter of IL-1B/IL-1RN were the risk of gastric cancer." (PMID 30479570, 2018). "Both, IL-1β and H. pylori infection have been associated to gastric cancer carcinogenesis." (PMID 29315242, 2018). "It is also emphasized on the investigation that the polymorphisms of IL1B gene may be involved in the high risk of the generation of gastric cancer." (PMID 30382864, 2018). "In addition, IL-1β inhibits gastric acid secretion and carriers of IL-1β polymorphisms producing higher IL-1β carry increased gastric cancer risk." (PMID 29686666, 2018). "Interleukin-1β (IL-1β) deregulation is responsible for the higher risk of gastric carcinoma." (PMID 30123433, 2018). "In human beings, IL-1β synergizes with H pylori and increases the risk of gastric cancer." (PMID 27713138, 2017). "Stratified analysis was performed by ethnicity, source of control, genotype method, and indicated a significantly increased gastric cancer risk associated with IL‐1B 31T variant in the population‐based subgroup (heterozygous model: OR = 1.22, 95% CI = 1.03–1.45)." (PMID 26805397, 2016). "Taken together, it is biological plausible that H. pylori may combined with IL‐1B 31T to confer increased susceptibility to gastric cancer." (PMID 26805397, 2016). "IL1B promoter polymorphisms were also associated with the presence of the CpG island methylator phenotype, a distinct phenotype with frequent aberrant DNA methylation of multiple CpG islands, in gastric cancers." (PMID 26823082, 2016). "The study suggested that IL‐1B 31 polymorphism might confer susceptibility to gastric cancer in the presence of H. pylori infection, indicating a gene–environment interaction in gastric carcinogenesis." (PMID 26805397, 2016). "Unlike their meta‐analysis involving both H. pylori and hepatitis C or hepatitis B virus, to the best of our knowledge, the current one is the first meta‐analysis to explore how H. pylori infection modified the association of IL‐1B 31 polymorphism and gastric cancer risk." (PMID 26805397, 2016). "Given its functional importance, potential functional polymorphisms in the IL‐1B gene that may influence IL‐1β production have drawn great attention for their association with gastric cancer risk." (PMID 26805397, 2016).
gastric cancer (continued). "In addition, PGC rs4711690 showed a significant interaction with IL1B rs1143623 in relation to gastric cancer risk (P value for interaction = 0.047, interaction index = 0.65)." (PMID 26158864, 2015). "In the gastric carcinoma patients, IL-1B-511*T/T homozygous allele represented 15.6% (5/32) of the case subjects, which was proportionally higher than in control group (12.0%; 13/108), however statistically with an OR of 2.349 (95% CI: 0.583–9.462) was not confirmed." (PMID 26401131, 2015). "This indicates that the T allele could act as a proinflammatory allele in genotype IL1B-31 T and both genotypes may constitute independent gastric carcinoma risk factors." (PMID 24803922, 2014). "Thus, H/K-ATPase-IL-1β transgenic mice confirm the genetic findings in human patients that elevated expression of IL-1β represents a risk factor for gastric cancer, and that IL-1β can synergize with Helicobacter infection to drive cancer formation." (PMID 24216700, 2013). "Stratification analyses of the IL-1B –511C/T polymorphism on gastric cancer susceptibility." (PMID 23704929, 2013). "Frequency of allele T of +3954C>T polymorphism of IL1B gene was higher in group of patients with chronic gastritis, atrophy, intestinal metaplasia, dysplasia or intestinal type of gastric cancer (32.1 %) as compared with population group (23 %), χ2 = 4.61 and p = 0.03." (PMID 23995914, 2013). "Another meta-analysis based on fourteen studies on the IL1B +3954 polymorphism covering data from six Asian and eight non-Asian populations showed lack of statistical significance between presence of studied polymorphism and risk of gastric cancer." (PMID 23995914, 2013). "It has been reported that the IL-1B -511T/IL-1B-31C alleles are significantly associated with the development of hypochlorhydria, H. pylori infection, gastritis, and stomach cancer, however the variability of results from studies conducted in various populations remain controversial." (PMID 20979650, 2010). "In the Thai population, IL-1B genotype -511CC is considered a risk factor for stomach cancer." (PMID 20979650, 2010). "While some researchers have found that IL-1B -511TT and IL-1B -31CC are proinflammatory, others have found, with in vitro experiments and with stomach cancer patients infected with H. pylori, that the IL-1B -511C and IL-1B -31T alleles potentiate expression of IL-1β in the gastric mucosa." (PMID 20979650, 2010). "According to their random-Odds Ratios, individuals carrying one of the IL-1RN *2, IL-1β -511T variant alleles or homozygotes for MTHFR 677T are significantly at higher risk of gastric cancer than those with the wild type homozygote genotypes, showing high PARs." (PMID 19506726, 2008). "However, to the best of our knowledge, no study has addressed the correlation of cytokine polymorphisms of IL-1β gene with the likelihood of cachexia from locally advanced gastric cancer." (PMID 17359523, 2007). "Thus, it is necessary to perform large-scale case-control studies considering lifestyle factors such as diet and drinking habits before a final statement of the role of IL-1B gene polymorphism in gastric cancer can be made." (PMID 17359523, 2007). "The IL-1B+3954 T allele is a major risk for cachexia from locally gastric cancer." (PMID 17359523, 2007). "In summary, the present study from this Chinese population provides evidence that IL-1β allele may contribute to the occurrence of cachexia associated with locally advanced gastric cancer." (PMID 17359523, 2007). "Besides these documented reports, the C-allele and CC genotype frequencies of IL-1β were observed with the risk of developing Graves’ disease in one study, along with another study of gastric carcinoma; both studies were conducted in the Kashmiri population of North India." (PMID 37371064, 2023).
gastric cancer (continued). "A number of DNA polymorphisms in TNF and STAT controlled cytokine genes have been mapped, including IL-1β, IL-1R, -8, -6, -17A, 17F, -22, that may mediate differences in response to chronic H. pylori infection and therefore risk for gastric cancer and reviewed." (PMID 35844493, 2022). "Moreover, for genetic background, polymorphisms in immune-related genes, such as IL-1B, IL-1RN, IL-10, could affect their expression and were suggested as risk factors of gastric cancer." (PMID 30479570, 2018). "Being a low penetrant SNP, IL‐1B 31 polymorphism might contribute to gastric cancer susceptibility; however, such risk effect seemed to be dependent on other risk factors, such as H. pylori infection, suggesting gene–environment interaction in gastric carcinogenesis." (PMID 26805397, 2016). "Working from assumption of substantial inflammatory contribution to cancer cachexia, we hypothesized that IL-1B-31 T/C, -511 C/T, +3954 C/T and IL-1RN gene polymorphisms have some relationship with the development of cachexia associated with locally advanced gastric cancer." (PMID 17359523, 2007). "Inflammasome activation is increasingly recognized in human gastric cancer and autoimmune gastritis, where it contributes to chronic inflammation and tissue damage through IL-1β and IL-18 production." (PMID 40673273, 2025). "In a gastric cancer model, triptolide demonstrated the ability to inhibit IL−8 expression induced by IL-1β, in addition to suppressing the activation of the AP-1 axes, mediated by ROS/ERK, and NF-κB, mediated by ROS." (PMID 40076871, 2025). "In this study, we found that IL-1β increased IL-8 expression, while Triptolide reduced this IL-1β-induced IL-8 expression in AGS gastric cancer cells." (PMID 39950099, 2024). "Increased expression of pro‐inflammatory cytokines and chemokines such as IL‐17A, IL‐22, and IL‐1 family members IL‐1β is involved in gastric cancer progression." (PMID 37306187, 2023). "In people with the interleukin-1 beta (IL-1B-31*C) and interleukin-1 receptor antagonist gene (IL-1RN*2/*2), genomes are more prone to develop stomach atrophy, stomach cancer, or hypochlorhydria brought on by H. pylori infection." (PMID 37159779, 2023). "IL-1β enhances migration, invasion, and metastasis in gastric cancer cells through elevated expression of MMP-2 and MMP-9." (PMID 36932407, 2023). "Desulfovibrio, a kind of sulphate-reducing bacteria, is enriched in gastric cancer patients and its metabolite (hydrogen sulphide) induces the production of NO and IL-1β to promote inflammation." (PMID 36839401, 2023). "The NLRP3 inflammasome regulates cyclin-D1, inducing IL-1β production to enhance differentiation of gastric cancer cells." (PMID 37081882, 2023). "In gastric cancer, piperine repressed IL-1β expression, resulting in inhibition of p38/MAPK and STAT3 activation." (PMID 36678600, 2023). "In gastric cancer, migration and invasion of cancer cells can be promoted by monocyte-derived IL-1β, which is stimulated by Mycoplasma hyorhinis in a TLR2-dependent manner." (PMID 36932407, 2023). "H. pylori infection weakens miR-22 expression and thus up-regulates NLRP3 inflammasome activation and release of oncogenic mature IL-1β, thereby triggering uncontrolled proliferation of epithelial cells and the occurrence of gastric cancer." (PMID 35795038, 2022). "The induction of apoptosis is related to BAX overexpression, BCL-2 downregulation, and inhibition of inflammation, as revealed by the downregulation of IL-6, TNF-α, IL-1β, and IL-8 which modulate cell growth proteins in gastric cancer cells." (PMID 36359261, 2022). "Studies have shown that transgenic mice that specifically express IL-1β can recruit a large number of myeloid-derived suppressor cells at an early stage and are more likely to develop spontaneous gastritis and gastric cancer." (PMID 35292015, 2022).